NRXN1 (neurexin 1)
Diseases named in the same sentence as NRXN1 in open-access papers (continued):
Sharing a sentence is not in itself a finding about the gene and the disease.
breast carcinoma (6 papers, 2015 to 2025). "Recent studies have linked NRXN1 overexpression to tumor progression and poor survival in multiple malignancies, including prostate cancer, breast cancer, and Ewing sarcoma." (PMID 40128298, 2025). "It was also found that the higher expression of NRXN-1 was associated with the advancement of the disease and distant organ metastases among breast cancer patients." (PMID 34659414, 2021). "Higher NRXN-1 mRNA expression was observed to be linked with the positive ER and PR status among breast cancer patients." (PMID 34659414, 2021). "High expression of neurexin-1 has been linked with carcinogenesis, invasion and proliferation in breast cancer, drug response in gastric cancer and to be predictive of a worse outcome in oral squamous cell carcinoma." (PMID 34403115, 2021). "The present study observed higher mRNA expression of NRXN-1 in breast cancer patients with higher age group (>50 years) menopausal status, patients with lymph node involvement compared to its counterpart." (PMID 34659414, 2021). "Breast cancer cases in the advanced stage of disease had 16.78-fold NRXN-1 mRNA expression while early-stage breast cancer patients showed 3.18-fold NRXN-1 mRNA expression and differences between them were found to be statistically significant (p < 0.0001)." (PMID 34659414, 2021). "Correlation analysis showed a significant negative correlation between miRNA-495 expression and NRXN-1 mRNA expression among the breast cancer patients while a positive correlation between NRXN-1 and CNTN-1 mRNA expression was observed." (PMID 34659414, 2021). "Therefore, the present study aimed to evaluate the prognostic importance of miRNA-495, NRXN-1, and CNTN-1 mRNA expression as well as the association of miRNA-495 expression with NRXN-1 and CNTN-1 mRNA expression among breast cancer patients." (PMID 34659414, 2021). "The present study observed decreased relative miRNA-495 expression (0.07-fold) while an increase in NRXN-1 (11.61-fold) and CNTN-1 (4.92-fold) was observed among breast cancer patients compared to healthy controls." (PMID 34659414, 2021). "Spearman correlation analysis was done between NRXN-1 and CNTN-1 mRNA expression among breast cancer patients." (PMID 34659414, 2021). "Breast cancer cases with positive menopausal status showed higher NRXN-1 mRNA expression (13.01-fold) compared to cases that do not have menopausal status (8.78-fold) and the expression differences among them was found to be statistically significant (p=0.03)." (PMID 34659414, 2021). "Breast cancer patients who had an ER and PR positive status showed 14.05- (p=0.03) and 15.29-fold (p=0.005) NRXN-1 mRNA expression while ER and PR negative patients showed 10.52- and 10.18-fold NRXN-1 mRNA expression, respectively." (PMID 34659414, 2021). "Potential oncogenes amplified in the breast cancer include GREB1, NRXN1, MGAT5, PKP4, DAPL1, ITGB6, and RBMS1, which may be implicated in carcinogenesis, proliferation, and invasion." (PMID 26432421, 2015). "Breast cancer patients with lymph node involvement had 15.70-fold higher NRXN-1 mRNA expression while breast cancer patients without any lymph nodes involvement had 8.40-fold NRXN-1 mRNA expression (p < 0.0001)." (PMID 34659414, 2021).
psychosis (6 papers, 2016 to 2025). "Taken together with CASKIN1’s close relationship with NRXN1, our data suggest that the identified variant is a strong candidate to be causing psychosis with high penetrance in this family." (PMID 36672919, 2023). "This is the first report of a common SNP variant of NRXN1 associated with enlargement of THLV volume in psychosis, and this volume is correlated with reduction of the hippocampus and enlargement of the caudate and choroid plexus." (PMID 31530798, 2019). "Although rare deletions of NRXN1 have been previously associated with psychosis, this is the first report of a common SNP variant of NRXN1 associated with enlargement of the THLV in psychosis." (PMID 31530798, 2019). "These facts support the potential role of this common variant of NRXN1 in psychosis." (PMID 31530798, 2019). "Although the role of this common NRXN1 SNP in psychosis is indirect, this study adds evidence to the role of NRXN1 in psychosis, which was originally implied by rare CNVs of this gene." (PMID 31530798, 2019). "Association analyses of age-at-onset, number of mood episodes, and presence of psychosis, substance abuse and/or suicidal ideation suggested modest contributions of genes such as RTN4, XKR4, NRXN1, NRG1/3 and GRK5 to disease characteristics." (PMID 38570518, 2024). "Definite proof of CASKIN1’s involvement in psychosis can only come from identification of additional families with similar pedigrees and mode of inheritance, yet our study strongly supports that CASKIN1 and the pre-synaptic signaling pathway involving it and NRXN1 warrants intensive study." (PMID 36672919, 2023).
small cell lung carcinoma (5 papers, 2020 to 2024). Small cell lung cancer (SCLC) is a highly aggressive malignant neoplasm, accounting for 10-15% of lung cancer cases, characterized byrapid growth, and early metastasis. "NRXN1 represents a single-pass transmembrane protein and has been recently described as a potential novel target for antibody–drug conjugate therapy in small cell lung cancer." (PMID 36503584, 2022). "NRXN-1 mRNA expression was analyzed in small cell lung cancer cell line such as SHP77 and NCI-H526 and it was found that the SHP77 had a higher mRNA expression, while NCI-H526 had comparatively low mRNA expression." (PMID 34659414, 2021). "NRXN1 may also be a new target for antibody–drug conjugate therapy in small cell lung cancer." (PMID 37041519, 2023).
Cognitive impairment (4 papers, 2011 to 2022). Abnormal cognition is characterized by deficits in thinking, reasoning, or remembering. "Fluctuations in NRXN1 levels and other neurexins are implicated in disrupting the balance of excitatory and inhibitory signals at synapses, resulting in damage and cognitive impairment seen early in AD." (PMID 33920138, 2021). "Interestingly, one recently published patient with a NRXN1 defect and no significant intellectual impairment was reported with similar malformations resembling the VACTERL spectrum." (PMID 21827697, 2011).
gastric cancer (4 papers, 2021 to 2024). A primary or metastatic malignant neoplasm involving the stomach. "The Exp (B) of NRXN1 is 0.284, which was also reported to be closely associated with gastric cancer." (PMID 35187167, 2022). "In the present study, we analyzed the DNA sequencing data of 229 patients from the TCGA-STAD project and identified five potential driver genes (CCDC169-SOHLH2, TTN, KNL1, C6, NRXN1) whose mutations were negatively associated with gastric cancer recurrence (p < 0.01)." (PMID 35187167, 2022). "NRXN1 (neurexin) normally functions as a synapse-organizing molecule, yet NRXN1 can act as a receptor for cell-cell interactions, and expression is highly related to recurrence of gastric cancers." (PMID 39715885, 2024). "NRXN1 is one of the SFARI genes, while MALAT1 was proven to be a risk gene for various cancers such as non-small cell lung cancer, hepatocellular carcinoma, gastric cancer, and pancreatic cancer." (PMID 33920310, 2021). "Five mutated genes, KNL1, NRXN1, C6, CCDC169-SOHLH2, and TTN, showed a significant negative correlation with the recurrence of gastric cancer through multivariable logistic regression analysis." (PMID 35187167, 2022).
mental disorder (4 papers, 2011 to 2025). A disease that has its basis in the disruption of mental process. "Several complex mental disorders are associated with mutations in NRXN1, along with dysfunction in the cerebellum, including ASD, SCZ, and intellectual disability." (PMID 35627176, 2022). "Mental disorders such as SCZ and ASD and many neuropsychiatric symptoms are associated with mutations in NRXN1 and its binding partners." (PMID 35627176, 2022). "The neurexin-1 knockout rat could therefore be used as a model for inappropriate or disinhibited social behaviour seen in childhood mental disorders." (PMID 38418646, 2025). "We have elucidated the connection between DISC1 and DISC1 pathway proteins such as NRXN1 and PDE4B to viral infection as well as to mental disorders." (PMID 35444632, 2022). "Several other genes that are dysregulated in mental disorders, such as DISC1, phosphodiesterase 4B (PDE4B), and neurexin-1 (NRXN1), could also be impacted by SARS-CoV-2 infection and contribute to neurotropism and inflammation in the CNS." (PMID 35444632, 2022).
Phelan-McDermid syndrome (3 papers, 2020 to 2024). A rare genetic neurodevelopmental disorder characterized by neonatal hypotonia, global developmental delay, normal to accelerated growth, absent to severely delayed speech, and minor dysmorphic features. "Third, given experience in rare genetic disorders such as Rett Syndrome and Phelan-McDermid syndrome, it is plausible that both loss of function and missense mutations in NRXN1 could contribute to risk for neurodevelopmental disorders." (PMID 32942984, 2020).
Pitt-Hopkins syndrome (3 papers, 2011 to 2024). Pitt-Hopkins syndrome (PHS) is characterized by the association of intellectual deficit, characteristic facial dysmorphism and problems of abnormal and irregular breathing. "A comparison between international consensus diagnostic criteria for Pitt-Hopkins syndrome (PTHS) and twins presenting with NRXN1-related disorder and followed by this institution were also presented." (PMID 39655047, 2024). "Results obtained in individuals with deletion of NRXN1 gene may show clinical signs sharing with the Pitt-Hopkins Syndrome (PTHS; OMIM#610954) and the affected patients have been classified under the term Pitt-Hopkins-like syndrome-2 (PTHSL2; OMIM#614325)." (PMID 39655047, 2024).
prostate carcinoma (3 papers, 2012 to 2025). A carcinoma that arises from epithelial cells of the prostate gland. "We show NRXN1 and NLGN1 expression in epithelial, endothelial, immune and neuronal cells in prostate cancer using cyclic immunofluorescence." (PMID 34911933, 2021). "Our cyclic IF analysis revealed the spatial distribution of NRXN1 and NLGN1 in prostate cancer and identified cell-type specific expression patterns for both proteins." (PMID 34911933, 2021). "To determine the expression pattern of NRXN1 and NLGN1 in prostate cancer across different cell types, we performed cyclic IF staining on tissue sections from eight patients in our cohort, using cell-type specific markers." (PMID 34911933, 2021). "We observe NRXN1 and NLGN1 are expressed in blood vessels in the prostate cancer tissue sections." (PMID 34911933, 2021). "The expression and function of NRXN1 and NLGN1 in prostate cancer have not been characterized before." (PMID 34911933, 2021).
Angelman syndrome (2 papers, 2019 to 2020). A neurogenetic disorder characterized by severe intellectual deficit and distinct facial dysmorphic features. "These are often observed in neurons derived from individuals with idiopathic forms of ASD, as well as from individuals with genetically defined forms of ASD such as SHANK3, 16p11.2 deletion and duplication, Angelman syndrome, Dup15q syndrome, NRXN1 mutations, and PTCHD1-AS." (PMID 32299488, 2020).
asthma (2 papers, 2022 to 2025). "Synergistic gene–environment interactions were identified for both TNS1 and NRXN1, with the highest risk of the combined asthma–eczema phenotype observed among ETS-exposed carriers of risk alleles." (PMID 41516222, 2025). "To investigate potential gene–environment interactions, we examined the combined effects of early-life ETS exposure and TNS1 and NRXN1 variants on the risk of developing the asthma–eczema phenotype." (PMID 41516222, 2025). "In conclusion, this study provides evidence that genetic variation in TNS1 and NRXN1 may interact synergistically with early-life ETS exposure to increase susceptibility to the combined asthma–eczema phenotype in children." (PMID 41516222, 2025). "Next, we explored whether the early-life ETS exposure interacts with TNS1 and NRXN1 variants to modulate the risk of developing the combined asthma–eczema phenotype." (PMID 41516222, 2025). "In this study, we evaluated whether early-life exposure to ETS interacts with genetic variants at two candidate loci, TNS1 and NRXN1, to impact the development of the combined asthma–eczema phenotype in children." (PMID 41516222, 2025). "Neurexin 1 has also been implicated in asthma and ASD pathology." (PMID 35492721, 2022). "We aimed to investigate whether variants in TNS1 and NRXN1—previously identified in a genome-wide interaction study—influence susceptibility to atopic eczema and the asthma–eczema phenotype and whether early-life environmental tobacco smoke (ETS) exposure modifies these genetic effects." (PMID 41516222, 2025). "Our study provides the first independent replication of these findings in a case-control setting, further supporting the hypothesis that TNS1 and NRXN1 contribute to the susceptibility underlying the asthma–eczema phenotype and that early-life environmental exposures modulate their effects." (PMID 41516222, 2025). "We found that TNS1 rs918949 was associated with an increased risk of the asthma–eczema phenotype, and gene–environment interaction analyses indicated that both TNS1 and NRXN1 variants conferred the greatest risk among children exposed to ETS in early life." (PMID 41516222, 2025). "This study resulted in the detection of four new SNPs, among which TNS1 and NRXN1 showed significant evidence for their interaction with ETS exposure in relation to the comorbidity of asthma and eczema." (PMID 41516222, 2025). "A key finding of this study is the significant interaction observed between the TNS1 rs918949 and NRXN1 rs10194978 variants and early-life ETS exposure in relation to the asthma–eczema comorbidity phenotype." (PMID 41516222, 2025). "Our findings provide the first independent replication of evidence suggesting that TNS1 and NRXN1 may contribute to the asthma–eczema comorbidity through mechanisms that could be substantially modified by early-life ETS exposure." (PMID 41516222, 2025). "Therefore, the present study aimed to investigate the role of SNPs in the NRXN1 and TNS1 genes in susceptibility to atopic eczema and to the eczema-associated asthma complex phenotype in children." (PMID 41516222, 2025). "Specifically, carriers of at least one risk allele of either TNS1 rs918949 or NRXN1 rs10194978 who were exposed to ETS had the highest risk of developing the combined asthma–eczema phenotype compared with nonexposed children carrying the wild-type genotype." (PMID 41516222, 2025). "Nevertheless, these results should be interpreted as preliminary, and the biological relevance of NRXN1 and ETS exposure on the risk of eczema-asthma comorbidity remains speculative at this stage." (PMID 41516222, 2025). "In this context, it is conceivable that early-life ETS enhances the effect size of the risk alleles at TNS1 and NRXN1, while conversely, these genetic variants may shape the extent to which ETS exposure increases the risk of eczema-associated asthma." (PMID 41516222, 2025).
asthma (continued). "In addition, we extended these analyses by evaluating the associations of TNS1 and NRXN1 variants with susceptibility to atopic eczema and to the eczema-associated asthma phenotype in children, irrespective of ETS exposure." (PMID 41516222, 2025). "Furthermore, the risk of the eczema-associated asthma phenotype among exposed children carrying the risk alleles fitted a multiplicative model, with ratios of relative risks of 4.70 for TNS1 and 2.16 for NRXN1, respectively." (PMID 41516222, 2025). "In one study, 43% of patients with a 2p16.3 deletion in NRXN1 were reported to have ASD and of these, 33.5% suffered from asthma and/or allergies." (PMID 35492721, 2022).
Astigmatism (2 papers, 2015). A type of refraction error associated with abnormal curvatures on the anterior and/or posterior surface of the cornea. "We conducted a meta-analysis on refractive astigmatism in CREAM, and found a significant hit with a marker downstream of the neurexin-1 (NRXN-1) gene (P = 3.92E−8)." (PMID 26386597, 2015).
epileptic encephalopathies (2 papers, 2017 to 2024). "Particularly in the context of exonic deletions in NRXN1, patients presenting with developmental and epileptic encephalopathies, mainly including infantile epileptic spasms syndrome, with early onset epileptic spasms, developmental delays, and progressive neurocognitive impairment." (PMID 39596051, 2024). "A causative genotype–phenotype correlation has not been definitely established; however, homozygous NRXN1 exonic deletions seem to be related to a variable clinical phenotype comprising ASD, severe ID, and epileptic encephalopathy." (PMID 39596051, 2024).
glioma (2 papers, 2021 to 2025). A benign or malignant brain and spinal cord tumor that arises from glial cells (astrocytes, oligodendrocytes, ependymal cells). "It is suggested that NRXN-1 is one of the key genes for glioma development and is linked to patient prognosis." (PMID 34659414, 2021). "It has been suggested that NRXN-1 is the key gene for glioma development and is related to the prognosis of patients." (PMID 34659414, 2021).
heart failure (2 papers, 2020 to 2024). Inability of the heart to pump blood at an adequate rate to meet tissue metabolic requirements. "Neurons from the patients who suffered from heart failure with DCM were divided into six subclusters with high expression of NRXN1." (PMID 38310240, 2024). "Depending on our results, the level of NRXN1 was concurrently found to be overexpressed in MI and heart failure samples." (PMID 33224271, 2020). "Therefore, according to the statement of previous research and the findings of the current study, we inferred that the inflammatory neurons with high expression of NRXN1 can trigger immune and inflammatory responses, which can contribute to the pathogenesis of heart failure." (PMID 38310240, 2024). "The probability of heart failure was significantly increased in patients with high expression of SOCS3 and NRXN1, while the expression of CDK6 and SMAD4 was significantly reduced in patients without heart failure." (PMID 33224271, 2020).
idiopathic dilated cardiomyopathy (2 papers, 2024 to 2025). Decreased function of the heart associated with cardiac enlargement and congestive heart failure, of unknown cause. "Idiopathic dilated cardiomyopathy is linked to mutations in the NRXN1 gene, indicating that LRRTM2 may affect heart disease by controlling NRXN1." (PMID 40520225, 2025).
microcephaly (2 papers, 2021 to 2023). A congenital or acquired developmental disorder in which the circumference of the head is smaller than normal for the person's age and sex. "Moreover, DLGAP2 interacts with NRXN1, a pre-synaptic cell-adhesion molecule and CASK, another scaffolding protein and mutations in both NRXN1 and CASK are associated to neurodevelopmental and neurocognitive disabilities and microcephaly." (PMID 33925474, 2021). "Weakening of the DLGAP2-NRXN1 interaction upon DLGAP2 haploinsufficiency and interfering with the NRXN1-CASK interaction might concur to microcephaly onset also in 8p23.2-pter patients." (PMID 33925474, 2021).
neuroblastoma (2 papers, 2021). Neuroblastoma (NB) is the most common solid, extracranial childhood tumor. "Further, miR-NID1 (Neurexin-1 (NRXN1) intron-derived miRNA, which corresponds to miR-8485) represses the expression of NRXN1 by binding to TDP-43 in neuroblastoma cell lines." (PMID 34069857, 2021).
Achalasia (1 paper, 2022). A disorder of esophageal motility characterized by the inability of the lower esophageal sphincter to relax during swallowing and by inadequate or lacking peristalsis in the lower half of the body of the esophagus. "In our study, there was a significant down-regulation of NRXN1 (Down FC: 9.07), suggesting that NRXN1 might be related to the onset of idiopathic achalasia." (PMID 35509690, 2022).